RNU6-422P (RNA, U6 small nuclear 422, pseudogene)
Gene: Small nuclear RNA gene on chromosome 10 (100,258,571 to 100,258,677, forward strand). Ensembl gene ENSG00000207362.
Homologues: Orthologues: macaque U6 (96% identical), chimpanzee U6 (95% identical). Paralogues in human: RNU6-43P (91% identical), RNU6-698P (89% identical), RNU6-11P (88% identical), RNU6-1216P (88% identical), RNU6-37P (88% identical), RNU6-398P (88% identical), RNU6-727P (88% identical), RNU6-774P (88% identical), RNU6-86P (88% identical), RNU6-1311P (87% identical), RNU6-140P (87% identical), RNU6-24P (87% identical), and 1287 more.